IFNGR1 (interferon gamma receptor 1)
Diseases named in the same sentence as IFNGR1 in open-access papers (continued):
Sharing a sentence is not in itself a finding about the gene and the disease.
infection (continued). "Infection of the progeny mice born to naïve KitW-sh/W-sh Ifnar1−/− Ifngr1+/+ mothers, with DENV2(D2Y98P) s.c., resulted in 30% mortality, compared to 90% mortality in KitW-sh/W-sh Ifnar1−/− Ifngr1−/− mice and lower clinical score, indicating the protective property of IFN-γ signaling." (PMID 34066286, 2021). "Infection of MC-deficient KitW-sh/W-sh Ifnar1−/− Ifngr1−/− mice lacking both type-I and type-II IFN receptors with DENV1-4 caused varying degrees of mortality and morbidity." (PMID 34066286, 2021). "I.d. infection of Ifnar1-/-;Ifngr1-/- mice by R. parkeri elicits disseminated, lethal disease." (PMID 34423779, 2021). "(c) Survival of Ifnar1-/-;Ifngr1-/- mice upon i.d. infection with 107 PFU of R. parkeri." (PMID 34423779, 2021). "Our observation that i.d. infection of DKO Ifnar1-/-;Ifngr1-/- mice causes eschar formation highlights the critical importance of interferons in restricting R. parkeri in mice and may reveal a key molecular determinant of human disease." (PMID 34423779, 2021). "In contrast with WT bacteria, i.d. infection of Ifnar1-/-;Ifngr1-/- mice with ompB::TnSTOPR. parkeri caused no lethality or weight loss." (PMID 34423779, 2021). "Ifnar1-/-;Ifngr1-/- mice were immunized with ompB or sca2 mutant R. parkeri by i.d. infection or with sca2 mutant R. parkeri by i.v infection and rechallenged 40 d later by i.d. infection with 105 WT bacteria." (PMID 34423779, 2021). "(b) Survival of Ifnar1-/-;Ifngr1-/- mice upon i.v. infection with 107R. parkeri." (PMID 34423779, 2021). "DENV2 could be detected in the serum of both KitW-sh/W-sh Ifnar1−/− Ifngr1+/+ and KitW-sh/W-sh Ifnar1−/− Ifngr1−/− mice during acute infection." (PMID 34066286, 2021). "We infected WT and Ifnar1-/-Ifngr1-/- mice, due to mouse availability, with CW3 or CW3I514F, and found that while CW3 infection led to dramatic weight loss of Ifnar1-/-Ifngr1-/- mice by 3 dpi, CW3I514F did not cause the same rapid morbidity." (PMID 33705489, 2021). "The ability of IFNγ to dampen myeloid cell IFNGR1 may also be important to ensure dampening of macrophage responsiveness in the context of infections where pathogen burden is insufficiently high to drive a strong type I IFN response." (PMID 31585982, 2019). "However, the survival rate of pups of pregnant IFNGR1-KO mice was higher than that of wild-type (WT) mice during infection." (PMID 29117241, 2017). "However, during infection FLAG staining correlated with an increase in cell surface IFNGR1 on monocytes from the infected fGR1 mice, when compared to those of infected WT C57Bl/6 mice." (PMID 28542482, 2017). "In addition, expression of c-Kit and Sca-1 remained unchanged on LIN− cells of Ifngr1-null mice at day 7 of infection indicating the dependence of Sca-1 induction on intact IFN-γ signaling." (PMID 23762028, 2013). "We have reported the down regulation of IFNGR1 following infection with M. tuberculosis." (PMID 22509293, 2012). "Initially Irgm1/m3(-/-) mice also developed high bacterial burden similar to the burden observed in Ifngr1-/- mice, yet by day 15 post-infection the number of organisms present in Irgm1/m3(-/-) mice was reduced to levels similar to the ones found in wildtype mice." (PMID 21731484, 2011). "With increasing time of infection at 12 hr post infection, we observed a sharp decline in the percentage of the colocalized IFNγR1 (32.7%) along with absolute failure of IFNγ to induce any detectable increase in the colocalization pattern at this condition (34.2%)." (PMID 21931549, 2011). "Although we noted some interesting differences in the ability of S.Tm θ to infect MLNs and spleen in Myd88−/− and Ifngr1−/− mice, infection levels remained lower than wildtype S.Tm and further studies are needed to define the function of the spv operon at these distal sites of infection." (PMID 40462990, 2025). "Notably, anti-IFN-γ treatment of Ifngr1−/−Nlrc4−/−Casp11−/− mice did not further enhance susceptibility to infection." (PMID 40885187, 2025).
infection (continued). "Furthermore, infection and vaccination with mutant R. parkeri strains showed that Ifnar1 −/−; Ifngr1 −/− double knockout mice may be a good tool for the study of rickettsial pathogenesis, and as models to evaluate vaccine candidates." (PMID 36556330, 2022). "It is worthy of note that at late hours of infection, though engaged IFNγR1 and IFNγR2 were simultaneously present in the non-raft fractions, they could not generate any productive interaction as evidenced by the complete absence of IFNγ triggered CoIP and/or phosphorylation signal." (PMID 21931549, 2011). "This process connects interferon-gamma receptor 1 to Janus kinase 2 (JAK2), potentially resulting in the activation of PD-L1, a known immunosuppressive molecule that perpetuates both infection and the wound healing process." (PMID 41271007, 2025). "Rescue of IFNGR1 levels was more apparent, but for IFNAR1, Tollip knockdown had a clear effect at 24 hours post-infection, and a more modest effect was evident at 36 hours post-infection." (PMID 40558091, 2025). "IF staining of mouse brains at day 7 post-infection showed that the levels of p-STAT1, IRF1, and PD-L1 in Ifnar1−/− and Ifngr1−/− mice were lower than those in control littermates." (PMID 38715061, 2024). "Macrophages were identified as the cluster expressing high levels of IFNGR1 and IFNGR2, then we investigated if macrophages responded to IFN-γ and were regulated by IFN-γ after the infection." (PMID 37180169, 2023). "In contrast, GSK 872 treatment significantly blunted infection-induced upregulation of IFN receptor subunits, including the type I IFN receptor subunits Ifnar1 and Ifnar2, and the type II IFN receptor subunits Ifngr1, and Infgr2." (PMID 38011306, 2023). "The IFN-γ signaling was blocked in the second infection model using either IFN-γ neutralization antibody or IFN-γ receptor 1 (Ifngr1) knockout mice." (PMID 35296070, 2022). "For this second-round infection, we were interested in confirming the attenuation of this line, so we used Ifng−/− (GKO) mice, which, like Ifngr1−/− mice, are highly sensitive to C. parvum infection." (PMID 33688009, 2021). "Inflammation steadily increased during the first week of infection, peaking at 7 DPI in WT and Ifng−/− mice and at 5 DPI in Ifngr1−/− mice." (PMID 31963302, 2020). "Gene signatures in the lung of SARS patients indicate that CXCL10, CCL2, interferon-α/β receptor 1 (IFNAR1), Interferon gamma receptor 1 (IFNGR1), and cluster of differentiation 58 (CD58) mRNAs are persistently generated during the infection." (PMID 32365944, 2020). "Virus titers in lungs at the peak of infection (3–6 dpi) were significantly higher (×101–102) in IFNAR-KO mice than in B6 (WT) and IFNγR1-KO mice, indicating that IFN type I mediated more effective virus control during X31 infection." (PMID 23785507, 2013). "Similarly, P. chabaudi infection of Ifngr1−/− mice (deficient in IFNG receptor) also resulted in increased ISG transcript abundance compared to mock-infected animals, implying that T1IFN signaling was also contributing to ISG expression during the early response to infection." (PMID 23144737, 2012). "When infected with 106 CFU of BCG, Ifngr1−/− × Ifng−/− double knock-out (DKO) mice were unable to control the infection and died within 12 wk of infection (unpublished data)." (PMID 18232731, 2008). "At the later time point, when Tollip levels were reduced, levels of IFNAR1 and IFNGR1 increased relative to the non-targeting control but remained lower than at the time of infection." (PMID 40558091, 2025). "The basis for this increase is not clear, but the decrease in IFNGR1 over the course of infection was evident." (PMID 40558091, 2025). "Over the course of infection, IFNAR1 and IFNGR1 decreased, whereas IFNAR2 remained stable." (PMID 40558091, 2025). "More importantly, Ifngr1-/- mice, but not WT or Ifnar1-/- mice, developed an eschar lesion at the infection site starting from day 6 p.i.." (PMID 38743761, 2024).
infection (continued). "Ifngr1-/- mice exhibited higher levels of total protein (TP) and globulin (GLOB) at days 6 and 10 p.i., indicating a more pronounced inflammatory response to infection." (PMID 38743761, 2024). "We first infected IFNG- and IFNGR1-knockout cell lines with HSV-1, a double-stranded DNA virus that can be propagated in the Vero cell line, at a multiplicity of infection (MOI) of 0.1 for 72 h and then observed the cytopathic effects daily under a light microscope." (PMID 35897807, 2022). "No or minor dermal lesions appeared at the site of infection in WT, single mutant Tlr4-/-, Ifnar1-/-, or Ifngr1-/- C57BL/6J mice or CD-1 mice." (PMID 34423779, 2021). "We report that intradermal infection of mice lacking both interferon receptors (Ifnar1-/-;Ifngr1-/-) with as few as 10 R. parkeri elicits eschar formation and disseminated, lethal disease." (PMID 34423779, 2021). "Although WT infection-specific regulation was observed only for TLR8 and IFNGR1, all four genes were expressed at higher levels (TLR8 and TLR9) or at lower levels (IFNGR1 and PYCARD) in the WT-infected dTHP1 cells than in the mock-treated or ΔrtxA1 mutant-infected dTHP-1 cells." (PMID 32817457, 2020). "Thus the results indicate prominent reduction in the ligand induced IFNγR1-IFNγR2 FRET efficiency, which is reduced by 64.6 % at 4 hr and 90.9 % at 12 hr post LD infection than the normal condition." (PMID 21931549, 2011). "Ifngr1−/− animals receiving Ifngr1+/+ bone marrow controlled the infection as efficiently as Ifngr1+/+ mice receiving Ifngr1+/+ bone marrow or mice with no graft." (PMID 18232731, 2008). "Consequently, preterm delivery observed in infected pregnant wild-type mice on day 6 post-infection did not occur in infected pregnant IFNGR1-KO mice as well as in PbNK65-infected pregnant IFNGR1-KO mice." (PMID 34644348, 2021). "Since KitW-sh/W-sh Ifnar1−/− Ifngr1+/+ and KitW-sh/W-sh Ifnar1−/− Ifngr1−/− mice were infected with DENV2 in the subsequent experiments, we also quantified the viremia on day 3 post-infection for this group, during acute infection, and on day 10 post-infection to check for viral clearance." (PMID 34066286, 2021). "Thus, mice lacking IFNγ, IFNGR1, or critical signaling components such as STAT1 are exquisitely susceptible to infections by Mycobacteria tuberculous, Listeria monocytogenes and other pathogens." (PMID 28542482, 2017). "However, in RAW 264.7 cells transduced with positive control shRNAs to knock down gene expression of IFN-γ receptor 1 (Ifngr1), 2 (Ifngr2) or Ticam2, the antiviral control by IFN-γ was greatly compromised and a 3- to 4-fold increase of infection efficiency was observed." (PMID 25268627, 2014). "Most striking of these results is that, though we could recover some ligand engaged IFNγR1 from non-raft portions at 4 hr post infection, IFNγR2 was only detectibly coimmunoprecipitated from the raft fractions." (PMID 21931549, 2011). "Therefore, we conclude that Irgm1/m3(-/-) mice do not exhibit an infection of extended duration as had been observed with the Ifngr1-/- mice." (PMID 21731484, 2011). "However, in contrast to Ot, R. parkeri also failed to induce lethal infection in Ifngr1-/- mice, indicating that IFN-I may compensate for IFN-γ in R. parkeri infection, but not Ot infection." (PMID 38743761, 2024). "To explore whether SECoVs infection affects IFN receptors expression, we next compared the receptor expression of the three types of IFNs, including type I IFN receptors (IFNAR1 and IFNAR2), type II IFN receptors (IFNGR1 and IFNGR2), and type III IFN receptors (IL10RB and IFNLR1)." (PMID 35126380, 2021). "Inhibition of lysosomal degradation by BafA1, which was added to the cells for 6 hours beginning 18 hours post-infection, partially rescued levels of IFNAR1 and fully rescued levels of IFNGR1 without significantly impacting viral N levels." (PMID 40558091, 2025).
infection (continued). "Following infection with SL1344 atp, gp91phox−/− mice had significantly increased bacterial loads in spleens and livers relative to wild type mice as did mice lacking IFNγR1." (PMID 19925904, 2010). "Thus, in the absence of IFN-γ, Ifngr1−/− mice displayed no rejection following HSCT, despite infection with BCG." (PMID 18232731, 2008).
cancer (44 papers, 2003 to 2025). A tumor composed of atypical neoplastic, often pleomorphic cells that invade other tissues. "Investigations on human cancer cells have shown that the reduced expression of immune-regulatory factors such as IFN-γ and IFNGR1 is tightly associated with poor prognosis and more aggressive behavior of cancer." (PMID 35386216, 2022). "The reduced expression of IFNGR1 is tightly associated with poor prognosis and more aggressiveness of cancer." (PMID 28479926, 2017). "Cancer cells could escape the effects of IFN-γ by downregulating or mutating molecules including IFNGR1/2, JAK2, and IRF1." (PMID 29299180, 2017). "Moreover, mutations in the genes encoding interferon gamma receptor 1 (IFNGR1) or its signal transducer Janus kinase 2 (JAK2) have been associated with poor disease outcome in various cohorts of patients with cancer receiving immune checkpoint inhibitors (ICIs)." (PMID 37604810, 2023). "Human IFNGR1 is a single pass membrane receptor with 489 amino acids and expressed in both cancer and immune cells." (PMID 39095793, 2024). "IFN-γ-induced PD-L1 expression has been reported in several cancer cells, and this mechanism is mostly mediated by activating IFNGR1/2-Janus kinase (JAK)/STAT1 pathways." (PMID 35269423, 2022). "In a rescue experiment, more cytotoxicity was observed in EGFR-CAR T cells when ICAM-1 was overexpressed on IFNγR1-KO cancer cells." (PMID 36085295, 2022). "Several studies reported that the defect in IFNGR1 will promote cancer cells that are unresponsive to immunotherapy, which finally leads to proliferation of cancer cells." (PMID 34124058, 2021). "Another relevant LR biomarker was IFNG binding to IFNGR1 and IFNGR2 (positive association for 17 of the 18 cancer types)." (PMID 34430923, 2021). "Cancers with EP300/CBP loss of function (LOF; deletion and/or copy number variants [CNV] loss) showed lower ERAP1 and IFNGR1 or HLA-A expression." (PMID 33602823, 2021). "Consistently, IFNGR1 was significantly downregulated in cancer specimens when compared to mucosa tissues." (PMID 27286456, 2016). "FBXO44 inhibition reactivates REs, leading to IFNγ signaling activation in cancer cells, as shown by the increased expression of IFNGR1, IFNGR2, and other ISGs and the decreased expression of protein tyrosine phosphatase nonreceptor type 2 (PTPN2), an IFNγ signaling inhibitor." (PMID 34385592, 2022). "This emphasizes the importance of the expression of IFNGR1 in the prevention of cancer." (PMID 28479926, 2017). "Additionally, cancer cell-derived EVs containing interferon gamma receptor 1 (IFNGR1), enhance PD-L1 expression on lymph node fibroblastic reticular cells (FRCs) through JAK1-STAT1 activation, resulting in CD8+ T cell depletion and potentially promoting lymph node metastasis of HNSCC." (PMID 40486875, 2025). "We thus performed mass spectrometry analysis on cancer cells treated with TAK-243 to discover candidate targets and found that IFN pathway effectors, including JAK1 and IFNGR1, were stabilized by TAK-243 treatment." (PMID 39540840, 2025). "Our data suggested a novel role of TPST2 in the regulation of cancer immunity, in which TPST2-mediated tyrosine sulfation of IFNGR1 at Y397 constrained IFNγ signaling." (PMID 39095793, 2024). "Another class of genes we examined was that of immune checkpoint-regulated genes, which include IFNGR1 and IRF1 (both of which are important for T cell recognition of cancer cells)." (PMID 37394010, 2023). "Decreased expression of IFNGR1 and STAT1 has demonstrated to decrease sensitivity of cancer cells to the immune response mediated by IFN-γ48–50." (PMID 37925508, 2023). "Recent research has indicated that the palmitoylation of proteins such as PDL1 and IFNGR1 can impact the levels of CD8+ T cell infiltration and influence the effectiveness of immunotherapy in human cancer." (PMID 37978524, 2023).
cancer (continued). "A recent study suggested that the knockout of genes in the IFN γ receptor signal pathway (IFNGR1, JAK1, or JAK2) endowed solid tumor cells with resistance to CAR-T cells by reducing the overall binding time and affinity of CAR-T cells with the cancer cells." (PMID 37889543, 2023). "Since IFN type I and IFN type II can induce the expression of PD-L1 in cancer cells, we also use siRNAs targeting IFNAR2 or IFNGR1 to silence expression of IFNAR2 or INFGR1 in HCC cells." (PMID 31379842, 2019). "Expression of other receptor molecules (IL13RA1, IL15RA, IL22RA1 and IFNGR1/2) was increased in carcinoma tissue, however due to our FC restriction we did not test these mRNAs for associations with miRNA differential expression." (PMID 30603058, 2018).
bacterial infection (6 papers, 2014 to 2025). "We conclude that down regulation of myeloid cell IFNGR1 contributes significantly to the enhanced susceptibility associated with type I IFN production during bacterial infection." (PMID 28542482, 2017). "Our findings thus suggest modulation of IFNGR1 is an important mechanism by which type I IFNs increase host susceptibility to bacterial infections." (PMID 28542482, 2017). "To test how these events might impact macrophage activation and host resistance during bacterial infection, we developed transgenic mice that express a functional FLAG-tagged IFNGR1 (fGR1) driven by a macrophage-specific promoter." (PMID 28542482, 2017).
infectious disease (6 papers, 2007 to 2023). A disorder directly resulting from the presence and activity of a microbial, viral, or parasitic agent in humans. "As the SNPs of this study had not yet been evaluated on PCM patients, we also compiled previous reports on the IL18 (-607 C/A, rs1946518 and -137 G/C, rs187238), IL12A (-504 G/T, rs2243115), and IFNGR1 (-611 A/G, rs13277474) SNPs and their association with diverse infectious diseases (respectively)." (PMID 33117339, 2020).
immunodeficiency (5 papers, 2015 to 2026). Failure of the immune system to protect the body adequately from infection, due to the absence or insufficiency of some component process or substance. "Another important primary immune disorder associated with increased susceptibility to mycobacterial infection is IFNGR-1 and IFNGR-2 deficiencies." (PMID 26137337, 2015). "IFNGR1, a key molecule in the interferon signaling pathway, activates macrophages and promotes Th1-mediated inflammatory responses, and the knockdown of IFNGR1 in mouse models has been associated with recovery from immune dysfunction and an increase in Tregs cells." (PMID 36769358, 2023).
adenocarcinoma (1 paper, 2016). A common cancer characterized by the presence of malignant glandular cells. "The tumors in Ifngr1−/−ApcMin/+ mice are more likely to progress into invasive adenocarcinomas." (PMID 27286456, 2016).
genetic disorder (1 paper, 2016). "Interferon-γ receptor 1 (IFNGR1) deficiency was the first identified genetic disorder recognized as MSMD." (PMID 27868075, 2016).